ABCB1 (ATP binding cassette subfamily B member 1)
Description:
Translocates drugs and phospholipids across the membrane. Catalyzes the flop of phospholipids from the cytoplasmic to the exoplasmic leaflet of the apical membrane. Participates mainly to the flop of phosphatidylcholine, phosphatidylethanolamine, beta-D-glucosylceramides and sphingomyelins. Energy-dependent efflux pump responsible for decreased drug accumulation in multidrug-resistant cells.
Synonyms: CD243; MDR1; PGY1; P-gp; GP170; ABC20; p-170; CLCS; ENPAT
Tractability: Small molecule: a drug acting on it is in phase 2 or 3 trials; a structure with a bound ligand is known; a high-quality ligand is known; it belongs to a druggable protein family. Antibody: UniProt places it where antibodies can reach, with high confidence; its Gene Ontology location is reachable by antibodies, with high confidence; UniProt predicts a signal peptide or a membrane-spanning region; the Human Protein Atlas places it where antibodies can reach. PROTAC: ubiquitination databases record sites on it; its protein half-life has been measured; a small molecule that binds it is known. Other modalities: a drug acting on it is in phase 2 or 3 trials.
Target class: ATP-binding cassette; ABCB subfamily; Transporter; Primary active transporter
Chemical probes: CHEMBL3582149, CHEMBL3582155, COMBRETASTATIN A4
Safety:
Unwanted effects reported when the protein is acted on. In parentheses: how it was acted on, where the effect was seen, and who reports it.
Lymphopenia (source: ClinPGx)
mucositis (source: ClinPGx)
adverse drug reaction scores (source: ClinPGx)
adverse effects (source: ClinPGx)
adverse events (source: ClinPGx)
adverse events and response to sevoflurane and remifentanil (source: ClinPGx)
adverse events, hand-foot syndrome, hypertension, or neutropenia (source: ClinPGx)
anemia (source: ClinPGx)
arthralgia (source: ClinPGx)
asthenia (source: ClinPGx)
bleeding (source: ClinPGx)
cardiotoxicity (source: ClinPGx)
CD4-cell count (source: ClinPGx)
chance of a prolonged hospital stay due to respiratory depression (source: ClinPGx)
clozapine plasma concentrations (source: ClinPGx)
clozapine plasma concentrations and agranulocytosis or neutropenia (source: ClinPGx)
clozapine-induced agranulocytosis or neutropenia (source: ClinPGx)
CNS depression (source: ClinPGx)
CNS depression in breast-feeding infants (source: ClinPGx)
constipation (source: ClinPGx)
diarrhea (source: ClinPGx)
diarrhea and skin rash (source: ClinPGx)
diarrhea and vomiting (source: ClinPGx)
drug toxicity (source: ClinPGx)
eGFR (source: ClinPGx)
estimated glomerular filtration rate (eGFR) (source: ClinPGx)
gastrointestinal toxicity (source: ClinPGx)
grade 1-2 neurotoxicity (source: ClinPGx)
hand-foot syndrome (source: ClinPGx)
hemorrhage (source: ClinPGx)
and 39 more effects
Gene: Protein-coding gene on chromosome 7 (87,503,017 to 87,713,375, reverse strand). Ensembl gene ENSG00000085563.
Subcellular location: Cell membrane; Apical cell membrane; Cytoplasm
Subcellular location (Human Protein Atlas): Plasma membrane
Pathways (Reactome):
Drug ADME: Abacavir transmembrane transport; Atorvastatin ADME; Prednisone ADME
Transport of small molecules: ABC-family protein mediated transport
Gene Ontology:
Molecular function: ABC-type xenobiotic transporter activity; ATP binding; ATPase-coupled intramembrane lipid transporter activity; ATPase-coupled transmembrane transporter activity; carboxylic acid transmembrane transporter activity; ceramide floppase activity; efflux transmembrane transporter activity; floppase activity; phosphatidylcholine floppase activity; phosphatidylethanolamine flippase activity; phosphatidylethanolamine floppase activity; protein binding; ubiquitin protein ligase binding; xenobiotic transmembrane transporter activity; transmembrane transporter activity; ABC-type transporter activity; ATP hydrolysis activity
Biological process: carboxylic acid transmembrane transport; ceramide translocation; export across plasma membrane; G2/M transition of mitotic cell cycle; phospholipid translocation; regulation of chloride transport; stem cell proliferation; transepithelial transport; xenobiotic detoxification by transmembrane export across the plasma membrane; xenobiotic transport across blood-brain barrier; response to xenobiotic stimulus; terpenoid transport; transmembrane transport; transport across blood-brain barrier; xenobiotic metabolic process
Cellular component: apical plasma membrane; cell surface; cytoplasm; extracellular exosome; membrane; plasma membrane; external side of apical plasma membrane
Genetic constraint (gnomAD): Loss-of-function variants: 64 observed, 136.94 expected, observed/expected ratio (o/e) 0.47, 90% interval 0.38 to 0.57. The upper end of that interval is the gene's LOEUF score, 0.57, which puts it in group 2 of 6, group 1 being the genes least tolerant of losing a copy. Missense variants: 1,271 observed, 1,572 expected, observed/expected ratio (o/e) 0.81, 90% interval 0.77 to 0.85. Synonymous variants: 511 observed, 547.8 expected, observed/expected ratio (o/e) 0.93, 90% interval 0.87 to 1.
Homologues: Orthologues: chimpanzee ABCB1 (99% identical), dog ABCB1 (91% identical), rabbit ABCB1 (87% identical), mouse Abcb1a (87% identical), rat Abcb1a (86% identical), pig ABCB1 (85% identical), guinea pig Abcb1 (82% identical), mouse Abcb1b (81% identical), Caenorhabditis elegans pgp-9 (45% identical), Caenorhabditis elegans pgp-1 (45% identical), Caenorhabditis elegans pgp-14 (39% identical), Caenorhabditis elegans pgp-12 (39% identical), and 5 more. Paralogues in human: ABCB4 (76% identical), ABCB5 (54% identical), ABCB11 (51% identical), ABCB9 (19% identical), ABCB10 (18% identical), ABCB8 (17% identical), TAP1 (16% identical), TAP2 (16% identical), ABCB6 (15% identical), ABCB7 (14% identical).
Diseases named in the same sentence as ABCB1 in open-access papers:
ABCB1 is named in the same sentence as 438 diseases in open-access papers, as found by Europe PMC text mining. Sharing a sentence is not in itself a finding about the gene and the disease. The quoted sentences say what the papers report.
breast carcinoma (411 papers, 1989 to 2026). "Sustained miR-21-dependent overexpression of P-glycoprotein, encoded by ABCB1, has been documented in several subtypes of breast cancer resistant to doxorubicin and Adriamycin." (PMID 41463125, 2025). "A recent study in a cohort of 179 patients with breast cancer identified higher expression of both ABCB1 and ABCC1 as associated with shorter duration of T-DXd treatment, and ABCB1 was also associated with shorter T-DXd-specific OS30." (PMID 41422323, 2025). "The variant allele of ABCB1 3435C>T (rs1045642) had an additive protective effect against cardiotoxicity in breast cancer patients treated with anthracyclines, and the results remained nominally significant after adjustment for clinical covariates." (PMID 38576421, 2024). "The prognostic role of ABCB1 polymorphisms and haplotype is also supported by studies on, inter alia, colorectal and breast cancer." (PMID 36755808, 2023). "This study critically discusses the latest data about the role of CYP3A4, CYP2D6, and ABCB1 gene polymorphism in the regulation of doxorubicin’s effects in breast cancer patients." (PMID 36358854, 2022). "For this reason, we decided to assess the contribution of ABCB1’s most common variants (i.e., G2677T/A in exon 21/rs2032582 and C3435T in exon 26/rs1045642) to the cancer therapy response in breast cancer patients." (PMID 35627114, 2022). "The survival analyses performed for breast cancer patients revealed a similar 10-year survival prognosis when comparing the patients with ABCB1 G2677T/A or C3435T polymorphic variants (VV) versus wild and heterozygous variants (WV and WW)." (PMID 35627114, 2022). "The combined genotype of ABCC2-24CC and ABCB1 3435CT or TT was related to the increased risk of bone metastases in Thai breast cancer patients treated with tamoxifen." (PMID 33801148, 2021). "Among various ABC transporters, the main ABC transporters primarily linked to MDR in breast cancer are P-glycoprotein (P-gp/MDR1/ABCB1), multidrug resistance-associated protein 1 (MRP1/ABCC1), and breast cancer resistance protein (BCRP/ABCG2)." (PMID 34959321, 2021). "The GT genotype of the rs2032582 variant in ABCB1 was further linked to improved breast cancer-specific survival (BCSS) compared with the GC/GA genotype in a study of 879 breast cancer patients who received FEC chemotherapy." (PMID 33801148, 2021). "A recent review demonstrated that three frequently studied polymorphisms in ABCB1 (rs1045642, rs1128503, and rs2032582) cannot be considered reliable predictors of response to chemotherapy in breast cancer patients." (PMID 33334016, 2020). "Although associations of ABCB1 gene expression with breast cancer prognosis were reported repeatedly, evidence for the role of its genetic variability in response to treatment is elusive." (PMID 33334016, 2020). "ABCB1 gene variants have been studied in several types of solid tumors treated with chemotherapy including ovarian, gastric and breast cancer." (PMID 31571407, 2019). "Other studies have also investigated the relationship between the C3435T polymorphism of ABCB1 gene and risk of breast cancer; whose results are also conflicting." (PMID 31547390, 2019). "Overexpression of ABCB1 in breast cancer is associated with poor response to first-line chemotherapies because ABCB1 can efflux many drugs used in the treatment of breast cancer such as taxanes, anthracyclines, and vinca alkaloids." (PMID 30897853, 2019). "Our correlation analysis also showed that the decreased level of EPB41L4A-AS2 in the docetaxel-resistant breast cancer cells was significantly associated with an increased level of ABCB1 mRNA." (PMID 30568280, 2018). "ABCB1 C3435T TT-carriers had lower risk of breast cancer events than any C-carriers (adjusted hazard ratio (HRadj) 0.74; 95%CI 0.49, 1.12), but only in non-statin users (Pinteraction = 0.042)." (PMID 30370250, 2018).
breast carcinoma (continued). "This study analyzed the correlation between the clinicopathological features of breast cancer patients and ABCB1 C3435T and ABCG2 C421A gene polymorphisms." (PMID 29340035, 2017). "For example, genetic polymorphisms of CYP1B1 and ABCB1 are associated with the clinical response to chemotherapy in breast cancer." (PMID 28085094, 2017). "A number of meta-analysis were undertaken to assess the association between ABCB1 C3435T polymorphism and risk of breast cancer." (PMID 27580695, 2016). "In this manuscript we evaluated the possible influence of ABCB1 C3435T polymorphism on the susceptibility of breast cancer as well as its correlation with the clinical features of Moroccan patients with breast cancer." (PMID 27580695, 2016). "In second place, we tried through the present study to evaluate the association between the ABCB1 C3435T polymorphism and breast cancer risk through a meta-analysis involving 16 studies with 6,094 cases of breast cancer and 8,646 controls." (PMID 27580695, 2016). "In the present study, we sought to assess the relationship between the C3435T polymorphism in ABCB1 gene and the risk of breast cancer in a sample of the Moroccan population." (PMID 27580695, 2016). "Several studies have investigated the relationship between the C3435T polymorphism of ABCB1 gene and risk of breast cancer; but the results are conflicting." (PMID 27580695, 2016). "In the present study, we have evaluated the association between the genetic polymorphism C3435T of ABCB1 gene and the risk of breast cancer among Moroccan patients." (PMID 27580695, 2016). "Further studies with a larger sample size, extended to other polymorphisms are needed to understand the influence of ABCB1 genetic variants on the risk of breast cancer." (PMID 27580695, 2016). "Several studies have investigated the relationship between the C3435T polymorphism in ABCB1 gene and the risk of breast cancer in different populations, however the results are inconsistent and the relevance of this polymorphism remains confusing." (PMID 27580695, 2016). "It is also necessary to remember that there are other polymorphisms in the ABCB1 gene implicated in the etiology of breast cancer which also deserve to be studied." (PMID 27580695, 2016). "Further analysis of genes associated with breast cancer, including ABCB1, BRCA1, GSTP1, IGF2, and TERT, showed a high CM fraction in cancer but non-CM in normal cell lines." (PMID 26659027, 2015). "The overexpression of ABCB1 has been associated with various cancers, such as acute myeloid leukemia, childhood tumors, breast cancers, hematological malignancies and solid tumors to name a few." (PMID 25191874, 2014). "In any case, the association of the evolutionarily more recent ABCB1 T-alleles in the SNPs examined with PgR- and ER-positivity in breast carcinomas is a novel finding meriting further investigation." (PMID 23935969, 2013). "A recent study identified ribophorin II (RPN2), part of an N-oligosaccharyl transferase complex, as a novel regulator of drug resistance via the regulation of the N-linked glycosylation of ABCB1 (P-glycoprotein) in breast cancer." (PMID 24212663, 2011). "Association of DNA methylation of ABCB1 and drug resistance in breast cancer cell-lines has been reported, and ABCB1 expression has been associated with poor outcome in breast cancer patients." (PMID 20056007, 2010). "This study shows an effect of menopausal status at diagnosis on the relationship between C3435T polymorphism of ABCB1 gene and the pharmacokinetics of docetaxel in breast cancer patients." (PMID 20628376, 2010). "In conclusion, these results show that menopausal status at diagnosis has an impact on the effect of C3435T polymorphism of ABCB1 gene on the pharmacokinetics of docetaxel in breast cancer patients." (PMID 20628376, 2010).
breast carcinoma (continued). "The ABCB1 c.3435T allele has been implicated in treatment outcomes of the antimalarials artemether and lumefantrine, mefloquine, warfarin stable-dose frequency and breast cancer chemotherapy." (PMID 37623436, 2023). "For instance, ABCB1 expression has been linked with increased metastasis in prostate cancer, uveal melanoma, and breast cancer patient cohorts, while the expressions of ABCB5 and of ABCC1 were up-regulated in metastases of patients and patients with melanoma, respectively." (PMID 37851804, 2023). "A similar result was observed in the surgically removed tissue: a high level of expression was associated with a low survival rate of breast cancer patients (55% in the group with high expression of ABCB1 versus 90% in the group with low expression, with a log-rank test p = 0.04)." (PMID 35631534, 2022). "However, for a deeper understanding of the role of ABCB1 polymorphisms in breast cancer therapy response, we performed the survival assessment in a 10-year follow-up of patients." (PMID 35627114, 2022). "Moreover, the ABCB1 polymorphism C1236T was significantly associated with docetaxel response in a study of 129 locally advanced South Indian breast cancer patients." (PMID 33801148, 2021). "Furthermore, it was shown that hypomethylation of ABCB1 downstream promoter is associated with increased ABCB1 expression and acquisition of multidrug resistance in breast cancer cells." (PMID 33753859, 2021). "ABCB1 expression might be associated with breast cancer molecular characteristics, the hypertensive status, tumour size, lymph node status, ethnicity, posttranscriptional events, epigenetic factors and ABCB1 gene variants." (PMID 33801148, 2021). "Likewise, rs1045642 was the only ABCB1 SNP to be significantly associated with a clinical characteristic of BC, namely, age at breast cancer diagnosis (p value = 0.029)." (PMID 31391850, 2019). "With regard to the clinical characteristics of BC, the ABCC2 SNPs rs2273697 and rs717620 were found to be significantly associated with age at breast cancer diagnosis and breastfeeding status, while the ABCB1 SNP rs1045642 was significantly associated with age at breast cancer diagnosis." (PMID 31391850, 2019). "Moreover, the ABCB1 SNPs rs1045642 and rs2032582 were significantly associated with age at breast cancer diagnosis and tumor size, respectively." (PMID 31391850, 2019). "A study that included 275 Mexican women enrolled in the Ella Binational Breast Cancer Study reported that the T allele of the c.3435C>T polymorphism located in exon 26 of the ABCB1 gene was an important risk factor for breast cancer in premenopausal women and specifically for the TNBC subtype." (PMID 30781715, 2019). "This study explored the hypothesis that the ABCB1 C3435T polymorphism confers effect modifications of statin use on three different breast cancer outcomes." (PMID 30370250, 2018). "Interestingly, we found that the cancer tissue of 16% breast carcinoma patients harbored gene mutations in the ABCB1 C3435T loci." (PMID 29340035, 2017). "In addition, the existence of the ZEB1/KLF5-mTOR-CCND1/ABCB1 axis may be involved in the paclitaxel response pathway, and it is influencing the susceptibility and prognosis of breast cancer." (PMID 38164285, 2024). "Overexpression of ABCB1 has been shown to be associated with drug resistance in a number of different tumour types, including ceritinib resistance in non-small cell lung cancer, and with poor clinical outcomes, such as response to chemotherapy in breast cancer." (PMID 31530935, 2020). "SIK3 may mediate ABCB1-associated drug resistance in breast cancer cells." (PMID 31762812, 2019). "In addition, down-regulation of miR-200c was also observed in the MCF-7 breast cancer cell line resistant to doxorubicin, also being associated with a poor chemotherapy response in human breast cancer patients in part by a possible upregulation of ABCB1 expression." (PMID 35582584, 2019).